ATP1A4 (ATPase Na+/K+ transporting subunit alpha 4)
Description:
Sperm-specific catalytic alpha subunit of the Na(+)/K(+)- ATPase responsible for ATP-dependent Na(+)/K(+) exchange across the plasma membrane. Transports 3 Na(+) ions out of the cell and 2 K(+) ions into the cell for each ATP hydrolyze. Plays an essential for sperm motility, capacitation, and male fertility by maintaining ionic gradients required for flagellar function and signaling (By similarity).
Synonyms: ATP1AL2
Tractability: Small molecule: an approved drug acts on it; a structure with a bound ligand is known; a high-quality ligand is known; it belongs to a druggable protein family. Antibody: UniProt places it where antibodies can reach, with high confidence; its Gene Ontology location is reachable by antibodies, with high confidence; UniProt predicts a signal peptide or a membrane-spanning region. PROTAC: ubiquitination databases record sites on it; a small molecule that binds it is known.
Safety:
Unwanted effects reported when the protein is acted on. In parentheses: how it was acted on, where the effect was seen, and who reports it.
atrioventricular block (inhibition, acute dosing; renal, cardiovascular; source: Lynch et al. (2017))
cardiac arrhythmia (inhibition, acute dosing; renal, cardiovascular; source: Lynch et al. (2017))
decreased heart rate (inhibition, acute dosing; renal, cardiovascular; source: Lynch et al. (2017))
increased cardiac contractility (inhibition, acute dosing; renal, cardiovascular; source: Lynch et al. (2017))
increased urinary sodium excretion (inhibition, acute dosing; renal, cardiovascular; source: Lynch et al. (2017))
increased urine excretion (inhibition, acute dosing; renal, cardiovascular; source: Lynch et al. (2017))
ventricular fibrillation (inhibition, acute dosing; renal, cardiovascular; source: Lynch et al. (2017))
vomiting (inhibition, acute dosing; renal, cardiovascular; source: Lynch et al. (2017))
Gene: Protein-coding gene on chromosome 1 (160,151,586 to 160,186,980, forward strand). Ensembl gene ENSG00000132681.
Subcellular location: Cell membrane
Pathways (Reactome):
Disease: Potential therapeutics for SARS
Muscle contraction: Ion homeostasis
Transport of small molecules: Ion transport by P-type ATPases
Gene Ontology:
Molecular function: ATPase-coupled monoatomic cation transmembrane transporter activity; P-type sodium:potassium-exchanging transporter activity; protein binding; kinase binding; ATP binding; ATP hydrolysis activity; nucleotide binding; P-type potassium transmembrane transporter activity
Biological process: flagellated sperm motility; potassium ion transmembrane transport; regulation of intracellular pH; sodium ion transmembrane transport; cell surface receptor signaling pathway; intracellular potassium ion homeostasis; intracellular sodium ion homeostasis; monoatomic ion transport; potassium ion import across plasma membrane; potassium ion transport; proton transmembrane transport; sodium ion export across plasma membrane; sodium ion transport; transport across blood-brain barrier; establishment or maintenance of transmembrane electrochemical gradient
Cellular component: photoreceptor cell cilium; rod photoreceptor outer segment; sodium:potassium-exchanging ATPase complex; sperm midpiece; membrane raft; plasma membrane; membrane
Genetic constraint (gnomAD): Loss-of-function variants: 83 observed, 113.38 expected, observed/expected ratio (o/e) 0.73, 90% interval 0.61 to 0.88. The upper end of that interval is the gene's LOEUF score, 0.88, which puts it in group 3 of 6, group 1 being the genes least tolerant of losing a copy. Missense variants: 1,197 observed, 1,346.5 expected, observed/expected ratio (o/e) 0.89, 90% interval 0.85 to 0.93. Synonymous variants: 506 observed, 509.32 expected, observed/expected ratio (o/e) 0.99, 90% interval 0.92 to 1.07.
Homologues: Orthologues: chimpanzee ATP1A4 (99% identical), macaque ATP1A2 (96% identical), rabbit ATP1A4 (86% identical), pig ATP1A4 (86% identical), mouse Atp1a4 (83% identical), guinea pig ATP1A4 (83% identical), rat Atp1a4 (83% identical), zebrafish atp1a3a (76% identical), zebrafish atp1a3b (75% identical), Caenorhabditis elegans catp-3 (37% identical), Caenorhabditis elegans catp-2 (36% identical), zebrafish si:dkey-28b4.8 (30% identical), and 11 more. Paralogues in human: ATP1A2 (78% identical), ATP1A1 (78% identical), ATP1A3 (77% identical), ATP12A (61% identical), ATP4A (59% identical), ATP2A2 (30% identical), ATP2A1 (29% identical), ATP2A3 (28% identical), ATP2B3 (28% identical), ATP2B2 (28% identical), ATP2B1 (27% identical), ATP2B4 (27% identical), and 9 more.
Diseases named in the same sentence as ATP1A4 in open-access papers:
ATP1A4 is named in the same sentence as 20 diseases in open-access papers, as found by Europe PMC text mining. Sharing a sentence is not in itself a finding about the gene and the disease. The quoted sentences say what the papers report.
male infertility (3 papers, 2018 to 2022). The inability of the male to effect fertilization of an ovum after a specified period of unprotected intercourse. "The significance of ATP1A4 in sperm physiology associates well with the current focus on identifying sperm proteins as biomarkers for improved fertility prediction and addressing male infertility." (PMID 35887284, 2022). "Its deficiency contributes to male infertility and multiple sperm dysfunctions, including low sperm motility and high intracellular sodium concentration, similar to the phenotype of Emc10 KO mouse, while overexpression of ATP1A4 in transgenic mice significantly increased sperm motility." (PMID 36077468, 2022). "Deducing downstream pathways mediated by ATP1A4 could help understand the molecular basis by which this protein functions in normal sperm, which in turn could help develop diagnostic approaches to identify male infertility." (PMID 36249829, 2018).
migraine (3 papers, 2007 to 2022). "DGR161 and DGR96 (p.Q1158H, CACNA1I) were found to carry variants in ATP1A4 (p.V146I and p.D685H), respectively, albeit the evidence for a role of this latter gene in migraine is still very limited." (PMID 35928792, 2022). "The ATP1A4 is a subunit of the sodium/potassium ATPase gene, which has been recently associated with a subtype of migraine, FHM." (PMID 17727731, 2007). "Overall our studies investigating potential migraine candidate genes in the chromosome 1q23 and 1q31 regions did not provide evidence implicating any of the tested variants of the ATP1A4, CASQ, KCNJ9 and 10, FasL, CACNA1AE genes in migraine." (PMID 17727731, 2007). "Furthermore, as ATP1A4 was recently reported as a tentative hemiplegic migraine gene, we also performed targeted analysis of WES data for rare functional variants in this gene." (PMID 33126486, 2020). "Six markers localised to the C1q23-C1q31 region covering several genes of interest (ATP1A4, CASQ1, KCNJ9 and J10, FasL and CACNA1E), have been analysed in regard to their potential association with migraine in a large population (243 migraineurs versus 243 healthy individuals)." (PMID 17727731, 2007).
deafness (1 paper, 2020). An inherited or acquired condition characterized by the complete loss of the ability to hear from one or both ears. "Of these genes, only one has been identified as causative for deafness in humans (DFNA7 and DFNA49): ATPase Na+/K+Transporting Subunit Alpha 4 (ATP1A4) on CFA38, which had a suggestive association in UK Dalmatians." (PMID 32413090, 2020).
diabetes (1 paper, 2020). "Both miR-1843b-5p and miR-1224-5p target Atp1a4 and Itpr3, which were connected to cGMP-PKG signaling, another typical pathway impaired in diabetes and obesity." (PMID 32350386, 2020).
diffuse large B-cell lymphoma (1 paper, 2020). "ATP1A4 expression was significantly higher in BRCA, lymphoid neoplasm diffuse large B-cell lymphoma and lung squamous cell carcinoma (all p < 0.001)." (PMID 32684846, 2020).
Infertility (1 paper, 2012). "Most of the key players in this process, CatSper 1–4, ATP1A4, sNHE, PKAs and sAC, are highly restricted to the male germ line and generate an infertility phenotype when the corresponding gene is subjected to functional deletion." (PMID 23508510, 2012).
melanoma (1 paper, 2016). A malignant, usually aggressive tumor composed of atypical, neoplastic melanocytes. "By microarray analysis we detected little or no expression of ATP1A2, ATP1A3 or ATP1A4 in xenografted melanomas or in normal human melanocytes." (PMID 27545456, 2016).
pulmonary TB (1 paper, 2016). "Therefore, we speculated that ATP1A4 may play a vital role in the occurrence of pulmonary TB by controlling ATP synthesis." (PMID 27655333, 2016).
seminoma (1 paper, 2023). A radiosensitive malignant germ cell tumor found in the testis (especially undescended), and extragonadal sites (anterior mediastinum and pineal gland). "In men with seminoma, a significant decrease in ATP1A4 in sperm may explain the reduction in sperm motility." (PMID 37174638, 2023).
testicular cancer (1 paper, 2023). A primary or metastatic malignant neoplasm that affects the testis. "Similarly, ATP1A4 was significantly decreased in asthenozoospermic testicular cancer patients." (PMID 37174638, 2023).
cancer (1 paper, 2020). A tumor composed of atypical neoplastic, often pleomorphic cells that invade other tissues. "Both ATP1A3 and ATP1A4 are sodium pump subunits in mammals, and thus, we proposed that these two proteins might be involved in the anti‐cancer effects of CS‐6 in GBM cells." (PMID 31746080, 2020).
tumor (1 paper, 2020). "Multivariate analysis showed that primary therapy outcome (p < 0.001), residual tumor (p = 0.001), ATP1A3 (p = 0.006), and ATP1A4 (p = 0.017) were independent risk factors for DSS." (PMID 32684846, 2020). "Multivariate analysis showed that primary therapy outcome (p < 0.001), residual tumor (p = 0.004), ATP1A2 (p = 0.006), ATP1A3 (p < 0.001), and ATP1A4 (p < 0.001) were independent risk factors for OS." (PMID 32684846, 2020). "Conversely, the expression of ATP1A2 and ATP1A4 was higher in normal ovarian tissues than in tumor tissues, and the high expression of ATP1A4 in OSC tissues was significantly correlated with prolonged OS and DSS." (PMID 32684846, 2020). "Conversely, the expression of ATP1A2 and ATP1A4 was lower in most tumor cell lines." (PMID 32684846, 2020). "Moreover, primary tumor outcome, residual tumor, ATP1A2, ATP1A3, and ATP1A4 were closely related to the risk of recurrence and mortality in OSC." (PMID 32684846, 2020). "Univariate analysis identified primary therapy outcome (p < 0.001), residual tumor (p < 0.001), ATP1A3 (p = 0.002), and ATP1A4 (p = 0.023) as prognostic factors for DSS." (PMID 32684846, 2020). "Based on the results of multivariate analysis, a genomic-clinical nomogram, including primary tumor therapy outcome, residual tumor, ATP1A2, ATP1A3, and ATP1A4, was established to predict the 1-, 3-, and 5-year OS and DSS in patients with OC." (PMID 32684846, 2020). "ATP1A1 and ATP1A3 were highly expressed in tumor tissues, whereas ATP1A2 and ATP1A4 were highly expressed in normal tissues (all p < 0.001)." (PMID 32684846, 2020). "Multivariate analysis showed that primary therapy outcome, residual tumor, and mRNA expressions of ATP1A3 and ATP1A4 were independent prognostic factors for both OS and DSS in patients with OSC." (PMID 32684846, 2020). "Univariate analysis identified primary therapy outcome (p < 0.001), age (p = 0.032), residual tumor (p < 0.001), ATP1A3 (p < 0.001), and ATP1A4 (p = 0.03) as prognostic factors for OS." (PMID 32684846, 2020). "Furthermore, we identified that primary therapy outcome, residual tumor, ATP1A3 gene, and ATP1A4 gene were independent indicators of OS and DSS in OSC." (PMID 32684846, 2020).
ATP1A4 also shares sentences with these, for which no sentence is quoted: asthenospermia (1 paper); breast tumors (1); Dupuytren’s Disease (1); familial hemiplegic migraine (1); latent infection (1); lung squamous cell carcinoma (1); lymphoid neoplasm (1); polycystic kidney disease (1).